ALB (albumin)
Diseases named in the same sentence as ALB in open-access papers (continued):
Sharing a sentence is not in itself a finding about the gene and the disease.
malnutrition (continued). "Finally, it is important to note that serum albumin, which is an important item in both the CONUT and PNI scores, is not a part of current definitions of malnutrition." (PMID 37510909, 2023). "In the case of both parameters, there was a statically significant difference between no malnourished patients and those with severe malnutrition (serum albumin p < 0.001, CRP p < 0.05) and between those with moderate and severe malnutrition (serum albumin p = 0.0013, CRP p = 0.0013)." (PMID 35276861, 2022). "In our cohort we observed that albumin tended to correlate with survival in NEN patients, but this fact suggests that the evaluation of serum levels of visceral proteins is not enough for the diagnosis of malnutrition in cancer patients." (PMID 35008278, 2021). "Often, they do not have clear signs of malnutrition/PEW according to the standard parameters, such as prealbumin or transferrin levels, and their albumin levels may be modulated more by type of dialysis than by other means." (PMID 32188148, 2020). "In contrast, in female, albumin and prealbumin only correlated positively with PA, and SPA; additionally, sarcopenia negatively correlated with BCM and PA; while the ECOG negatively correlated only with FFMI, SMI, BCMI, and BCM; finally, malnutrition did not correlate with FM of FMI in women." (PMID 39447215, 2024). "In the NPS scoring system, patients with serum albumin <40 g/L were considered to have malnutrition, while the threshold for serum albumin was 35 g/L in the CONUT scoring system, which led to its poor ability to distinguish patients with and without malnutrition." (PMID 35284455, 2022). "Therefore, it is difficult to interpret low albumin levels in patients withactive tuberculosis without other parameters to assess APR and malnutrition, since lowalbumin levels may reflect both APR to infection and protein deficiency." (PMID 25029650, 2014).
Hypoalbuminemia (1,997 papers, 2003 to 2026). The concentration of albumin in the blood circulation is below the lower limit of normal. "Independent predictors of mortality included severe dengue classification, intensive care unit admission, elevated neutrophil-to-lymphocyte ratio, and hypoalbuminemia, with albumin emerging as the strongest single biomarker for risk prediction." (PMID 42060660, 2026). "This distinction is clinically critical because increases in Bf caused by displacement, hypoalbuminaemia, or HSA mutations that reduce bilirubin affinity are often undetectable by TSB measurement alone." (PMID 41144788, 2026). "Albumin levels have been associated with furosemide efficacy and hypoalbuminemia, often due to increased capillary permeability, is linked to poorer outcomes and higher mortality." (PMID 41598701, 2026). "In thoracic surgical populations, both preoperative hypoalbuminemia and perioperative albumin decline have been associated with a higher incidence of PPCs." (PMID 41598637, 2026). "The neutrophil percentage is a well‐established marker of inflammation, and a low serum albumin level (i.e., hypoalbuminemia) is also associated with the severity of inflammation and a heightened susceptibility to infectious complications." (PMID 41543379, 2026). "Although hypoalbuminemia is widely recognized as a risk factor for postoperative mortality, limited evidence exists on the predictive value of postoperative albumin levels specifically after hip fracture surgery." (PMID 41303773, 2025). "Many studies have confirmed that preoperative hypoalbuminemia (serum albumin concentration was lower than 35 g/L) is a risk factor for pulmonary complications." (PMID 40225039, 2025). "Hypoalbuminemia in early SAP has been associated with poor prognosis, and timely albumin infusion can reduce mortality in SAP patients with hypoalbuminemia." (PMID 40761871, 2025). "Traditionally, albumin is regarded as a nutritional marker, and numerous postoperative complications are associated with hypoalbuminemia." (PMID 40432957, 2025). "The albumin corrected anion gap (ACAG) adjusts for hypoalbuminemia, thereby enhancing diagnostic accuracy in critically ill patients." (PMID 41401154, 2025). "While serum albumin is a general marker of disease severity, hypoalbuminemia is particularly associated with a poor prognosis." (PMID 40821648, 2025). "ALB, a key nutritional marker, reflects metabolic status, with hypoalbuminemia linked to increased mortality." (PMID 41357195, 2025). "Supportive treatments included packed red blood cell transfusions for severe anemia, human albumin supplementation to correct hypoalbuminemia-associated edema, and intravenous immunoglobulin for immunomodulation." (PMID 41164818, 2025). "A significant decrease in serum albumin in our sample also confirms that hypoalbuminemia is associated with mortality." (PMID 40017475, 2025). "Recent meta-analyses have demonstrated a significant association between hypoalbuminemia and worse survival outcomes, highlighting the prognostic importance of albumin in patients receiving ICIs." (PMID 40217668, 2025). "This study aimed to identify albumin cutoff values defining hypoalbuminemia and describe the association between serum albumin and outcomes in patients with spinal metastases." (PMID 40103850, 2025). "Although total protein, albumin, and globulin levels remained relatively unchanged, hypoalbuminemia—another marker of AKI—has been strongly associated with poor outcomes." (PMID 41030349, 2025). "Age over 65, previous antibiotic exposure within 90 days, and hypoalbuminemia (serum albumin <3 g/dL) were all significantly associated with the composite outcome." (PMID 41439186, 2025). "In the final part of the study, we examined potential risk factors for hypoalbuminemia (serum albumin < 3.0 g/dL)." (PMID 41375027, 2025).
Hypoalbuminemia (continued). "Hypoalbuminemia, a deficiency in albumin, has been associated with various dysfunctions, including abnormal activation of systemic inflammation, reduced drug response, and compromised immune function." (PMID 39067064, 2025). "Hypoalbuminemia, which worsens with age, is associated with both malnutrion and inflammation, and prior studies have identified albumin as a potential biomarker for frailty." (PMID 40416687, 2025). "Albumin levels were low at baseline, affecting 73.68% (462 out of 627) of the cats, which likely indicates the hypoalbuminemia commonly associated with FIP." (PMID 41360910, 2025). "This case emphasizes the importance of considering PLE in the differential diagnosis of unexplained edema and hypoalbuminemia in cancer patients and highlights the diagnostic utility of albumin scintigraphy in preoperative evaluation." (PMID 41497708, 2025). "In women with preeclampsia, elevated urinary albumin excretion leads to hypoalbuminemia, which is linked to damage in the glomerular endothelial glycocalyx, podocytes, and tubuleinterstitium." (PMID 39857389, 2025). "Higher serum albumin was strongly protective, whereas hypoalbuminemia was associated with increased mortality." (PMID 41379187, 2025). "Hypoalbuminemia in hemodialysis (HD), commonly defined as serum albumin <3.5 g/dL, is multifactorial and linked to adverse outcomes, including higher hospitalization rates." (PMID 41552166, 2025). "When renal function declines, especially with glomerular filtration membrane damage as in diabetic nephropathy, increased glomerular permeability leads to urinary albumin loss, causing hypoalbuminemia." (PMID 40860624, 2025). "Another study similarly demonstrated that individuals with hypoalbuminemia faced a notably increased risk of developing osteoporosis in comparison with individuals with normal albumin levels." (PMID 40661684, 2025). "Serum albumin levels were also significantly lower in this group (median 2.00 g/dL vs. 3.30 g/dL; p < 0.001), consistent with hypoalbuminemia, which is associated with systemic inflammation and capillary leakage." (PMID 40733567, 2025). "Overall, hypoalbuminemia was generally found to be associated with shorter survival time and increased risk of mortality, while high albumin trended towards longer survival times and decreased risk of short-term mortality." (PMID 40103850, 2025). "A prospective study in community-dwelling older adults showed that hypoalbuminemia (serum albumin <3.8 g/dL) was associated with a 2.3-fold higher risk of incident sarcopenia, likely via limiting muscle protein synthesis." (PMID 41280389, 2025). "When ALB levels were dichotomized at a threshold of 35.0 g/L, patients with hypoalbuminemia exhibited a 1.78-fold higher mortality risk." (PMID 41393124, 2025). "Our findings indicate a significant positive association between higher DI-GM scores and increased serum albumin levels, with a consistent reduction in the odds of hypoalbuminemia across all models." (PMID 40396178, 2025). "Management of hypoalbuminemia should indicate correcting any underlying cause of inflammation prior to supplementation of albumin via infusion." (PMID 40951243, 2025). "Despite the strong apparent link between hypoalbuminemia and poor outcomes in a range of oncologic patients, the order of causality between acute illness and serum albumin level is still unclear." (PMID 40103850, 2025). "Patients with GI cancer often experience hypoalbuminemia due to factors such as GI obstruction, malabsorption, inhibition of liver synthesis by the tumor, and increased consumption of albumin caused by fast tumor cell proliferation and active cell metabolism." (PMID 40271430, 2025). "Our study identify hypoalbuminemia as a statistically independent risk factor for rebleeding, existing evidence consistently demonstrates that low serum albumin (ALB) independently predicts rebleeding and mortality." (PMID 41585275, 2025).
Hypoalbuminemia (continued). "Hypoalbuminemia, defined as serum albumin levels below 35 g/L, has been strongly associated with adverse surgical outcomes, including impaired wound healing, higher infection rates, prolonged hospitalization, and increased mortality." (PMID 40161084, 2025). "In accordance with previous studies, some laboratory test indicators for poor nutrition, including pre‐ and post‐surgical low albumin level, hypoalbuminemia, and anemia, were significantly associated with AL regardless of gender." (PMID 40346009, 2025). "The primary mechanism by which hypoalbuminemia increases cardiovascular risk is the diminished antioxidant, oncotic pressure-maintaining, and antithrombotic capacities of albumin." (PMID 40171185, 2025). "Serum albumin remains a key biomarker for evaluating nutritional status, and numerous studies have linked hypoalbuminemia to poor prognosis in malignant tumors." (PMID 41398263, 2025). "Albumin serves as the carrier of acquired immune antibodies, and hypoalbuminemia is often associated with immune dysfunction." (PMID 40686821, 2025). "Serum albumin is a well-established prognostic marker in GC, with hypoalbuminemia linked to higher risks of complications and poor survival." (PMID 40572703, 2025). "The disease is also associated with hypoalbuminemia due to leakage of albumin into the gastric lumen." (PMID 41209104, 2025). "The slope was the steepest at lower albumin levels, indicating a disproportionately high risk in patients with hypoalbuminemia." (PMID 40572703, 2025). "Despite most studies finding hypoalbuminemia to be associated with at least one of the examined outcomes, the serum albumin cutoff level used to define hypoalbuminemia in our included studies was inconsistent." (PMID 40103850, 2025). "A further immunological cascade boosts IL-6 and IL-1β levels, causing increased blood vessel permeability, leading to transcapillary albumin loss and hypoalbuminemia." (PMID 41008744, 2025). "She presented with chronic iron deficiency anemia (Hgb 6.2 g/dL), hypoalbuminemia (albumin 1.8 g/dL), multiple electrolyte deficiencies, neuropathy, edema, and chronic diarrhea." (PMID 41214407, 2025). "Sepsis-associated hypoalbuminemia results largely from systemic capillary leak syndrome and hepatic reprioritization of protein synthesis towards acute-phase reactants over albumin." (PMID 40766844, 2025). "All patients exhibited severe hypoalbuminemia (mean albumin level of 17.2 g/L), iron deficiency anemia (mean hemoglobin level of 104.67 g/L), and micronutrient deficiencies." (PMID 41323009, 2025). "Albumin, a marker of nutritional status, is associated with key outcomes such as wound healing, infection risk, and survival, with hypoalbuminemia exacerbating inflammation and immune dysfunction." (PMID 41179670, 2025). "Albumin levels are also important in patients with excessive inflammation, such as burns and acute pancreatitis, and hypoalbuminemia is also associated with the risk of infection." (PMID 40095884, 2025). "Conversely, vitamin D and serum albumin levels were lower in the severe group, echoing prior reports associating hypoalbuminemia and vitamin D deficiency with heightened inflammation, vascular leakage, and poor clinical outcomes." (PMID 40430232, 2025). "The total albumin loss normalized to body weight averaged 0.9 g/kg, still highlighting the need of possible replacement in case of pre-existing hypoalbuminemia." (PMID 40559765, 2025). "This study demonstrates that preoperative hypoalbuminemia (serum albumin<35 g/L) is significantly associated with adverse postoperative outcomes in patients undergoing open abdominal surgery." (PMID 40161084, 2025). "Among laboratory parameters, elevated NLR, reduced PNI, glycated hemoglobin (HbA1c) ≥ 7%, and hypoalbuminemia (serum albumin < 3.8 g/dL) emerged as significant and independent risk factors for SWI development." (PMID 40868811, 2025).
Hypoalbuminemia (continued). "Hypoalbuminemia, i.e., a reduced level of serum albumin, is also noted in patients with NS, which is caused by albuminuria, which is caused by increased glomerular permeability." (PMID 40868160, 2025). "Thesestudies added further evidence for the detrimental effects of hypoalbuminemia inCVD, and that low serum albumin should be considered as a risk factor forincreased mortality in patients with CHD." (PMID 40927110, 2025). "Regarding albumin level, hypoalbuminemia is associated with unfavorable outcomes after cardiac surgery." (PMID 40555869, 2025). "Prior studies have linked hypoalbuminemia—an important marker of nutritional status and a marker of illness—to poorer outcomes in hospitalized patients and identified low serum albumin as a marker of higher mortality risk in PAH." (PMID 40941614, 2025). "More commonly, hypoalbuminemia is associated with kidney failure and permeability of the gut, causing albumin to leak into the blood." (PMID 40073124, 2025). "Studies carried out on individuals with hypoalbuminemia caused by ailments other than nephrotic syndrome have also exhibited a link between low levels of plasma albumin and a deficiency of vitamin D." (PMID 40051558, 2025). "Low albumin levels are a strong predictor of liver decompensation and are generally associated with an increased risk of infection because hypoalbuminemia indicates poor nutritional status and immune function." (PMID 40332100, 2025). "In these patients, hypoalbuminemia has been proposed to be caused by chronic systemic inflammation and reduced synthesis of albumin." (PMID 39906535, 2025). "Hypoalbuminemia is indicative of a weakened immune system, indicating that serum albumin is associated with the strength of the host immune system." (PMID 40936483, 2025). "Lower serum albumin levels were associated with an increased incidence of postoperative hypoalbuminemia in children with CHD (OR: 3.12, 95% CI: 1.66–5.84)." (PMID 39896721, 2025). "Hypoalbuminemia, common in these patients, indicates poor nutrition and weakens immunity, raising the death risk, with sepsis—related inflammation further lowering albumin." (PMID 40104144, 2025). "Specifically, they observed that patients with hypoalbuminemia, characterized by lower levels of albumin, had a higher risk of severe disease outcomes." (PMID 40699702, 2025). "Patients with hypoalbuminemia exhibited increased inflammatory markers and higher mortality, consistent with previous research indicating that low albumin levels are associated with poor prognosis in critically ill patients." (PMID 40310418, 2025). "Serum albumin levels are not only indicative of the body’s nutritional reserves, but low levels (hypoalbuminemia) are also closely linked to poor postoperative recovery and the onset of cachexia." (PMID 41415846, 2025). "Albumin was supplemented to correct the hypoalbuminemia caused by chronic hepatitis B, and antibiotics were administered to control urinary tract infection." (PMID 40922353, 2025). "Low ALB levels, known as hypoalbuminemia, are associated with poor prognosis in various cancers, indicating its role in cancer biology." (PMID 40013138, 2025). "Previous studies have shown that hypoalbuminemia (serum albumin concentration <30 g/L) is significantly associated with increased intestinal permeability." (PMID 40917860, 2025). "PIV also correlates with CRP and hypoalbuminemia—features of the CRP/albumin ratio—previously linked to increased osteoporosis risk." (PMID 41140653, 2025). "A diminished serum albumin concentration, termed hypoalbuminemia, has been consistently linked to adverse outcomes in a range of malignancies, highlighting its relevance in tumor biology." (PMID 40693202, 2025). "Given the independent association found between admission hypoalbuminemia and 30-day readmission risk after hip fracture, our institution has already incorporated serum albumin testing into perioperative assessment and risk stratification pathways." (PMID 38528491, 2024).